ALB (albumin)
Diseases named in the same sentence as ALB in open-access papers (continued):
Sharing a sentence is not in itself a finding about the gene and the disease.
type 1 diabetes (104 papers, 2002 to 2026). "Early prospective studies suggested that around 30–50% of people with type 1 diabetes will develop microalbuminuria, in whom a 6% increase in risk of coronary heart disease is seen per 5 mg increase in 24-h albumin excretion rate (AER)." (PMID 34979961, 2022). "HbA1C and circulating fructosamine albumin were higher in individuals with type 1 diabetes at high versus low DKD risk." (PMID 33941808, 2021). "The second objective was to ascertain if sAF aligned with risk for kidney disease, defined by the presence of type 1 diabetes and urinary albumin excretion tertile." (PMID 33941808, 2021). "Risk for DKD is defined as an increase in urinary albumin excretion during puberty, preceding micro- and macroalbuminuria, as seen in adolescents with type 1 diabetes in the upper third of urinary albumin excretion." (PMID 33941808, 2021). "In clinical studies, circulating UA has been linked to serum glycated albumin in hyperuricemia men and glycosylated hemoglobin in women with type-1 diabetes." (PMID 33426022, 2020). "During a median of 5.8 years follow-up, baseline mannose-binding lectin was associated with increased urinary albumin excretion in patients with type 1 diabetes." (PMID 29910771, 2018). "Low vitamin C levels in type 1 diabetes are associated with increased transcapillary albumin escape and increased atherosclerotic damage as evidenced by a negative relationship to IMT in children." (PMID 26783536, 2016). "During the last century, landmark studies of type 1 diabetes considered the natural history of DKD as progressive increase of urine albumin excretion followed by GFR loss and the development of ESKD." (PMID 28197499, 2016). "The CKDGen consortium meta-analysis identified a missense SNP in CUBN (rs18801239) associated with urinary albumin/creatinine ratio and clinical microalbuminuria in the general population, an association replicated in an AA cohort with type 1 diabetes and later in the Framingham Offspring Study." (PMID 32379818, 2020). "PON1 polymorphisms were also studied in another Caucasian population with type 1 diabetes mellitus (T1DM), where it was found that genotypes LL on 55, AA (–162) and GG (–1074), were associated with an increased urinary albumin loss." (PMID 38982880, 2024). "Consistently, a study by Lee confirmed that cilostazol ameliorates albuminuria and restores serum albumin levels in rats with type 1 diabetes." (PMID 38525134, 2024). "The first detectable sign of kidney problems in the “traditional” course of type 1 diabetes-related kidney disease is elevated amounts of the protein albumin in the urine, termed albuminuria." (PMID 38192517, 2023). "In fact, there are reports that urinary zinc excretion in diabetic patients is approximately twice that in healthy controls; urinary zinc excretion is also significantly higher in type 1 diabetes with microalbuminuria than with normal albumin." (PMID 36539708, 2022). "One short study did suggest a significant reduction in urine albumin:creatinine ratio (UACR) in 89 individuals with type 1 diabetes who were normotensive and normoalbuminuric and who were treated with placebo or perindopril for 4 months." (PMID 34979961, 2022). "It has been reported that mTORC2 plays a critical role in Nox4-derived ROS generation and podocyte apoptosis, which contributes to urinary albumin excretion in type 1 diabetes." (PMID 33046439, 2021). "In a type 1 diabetic mouse model, the expression of nephrin decreases and urinary albumin excretion increases as the expression of TGF-β increases." (PMID 33050674, 2020). "Mean serum MBL levels were significantly higher in Danish adults with type 1 diabetes and normal urine albumin levels than in healthy age- and sex-matched control subjects." (PMID 31117958, 2019). "In 909 patients with type 1 diabetes, there was a difference in the relationship between urinary albumin excretion and circulating fibrinogen in males and females." (PMID 29910771, 2018).
type 1 diabetes (continued). "Cow's milk albumin has also been suggested in the etiology of type 1 diabetes due to milk peptide antibody (bovine serum albumin antibodies) binding to beta-cell-specific surface protein and promoting islet cell destruction." (PMID 28819632, 2017). "In fact, clinical studies in patients with type 1 diabetes revealed a significant increase in the skin concentration of AGEs as urinary albumin increased from normal to microalbuminuria, and macroalbuminuria." (PMID 28141808, 2017). "In patients with type 1 diabetes an increase in albumin excretion has traditionally been taken as equivalent to decline in GFR." (PMID 27375689, 2016). "In a type 1 diabetic rat model, resveratrol treatment blunted the increases of urine albumin excretion, kidney weight and creatinine clearance rate." (PMID 24312656, 2013). "C peptide has the capacity to diminish glomerular hyperfiltration and reduce urinary albumin excretion in both experimental and human type 1 diabetes." (PMID 20535267, 2010). "After quality control, next-generation sequencing data were available for a total of 1064 individuals, of whom 541 had developed either severe albuminuria or end-stage kidney disease, and 523 had retained normal albumin excretion despite a long duration of type 1 diabetes." (PMID 39103720, 2024). "We hypothesised that adolescents with type 1 diabetes with a urinary albumin/creatinine ratio (ACR) in the upper tertile of the normal range (high ACR) are at greater risk of three-step diabetic retinopathy progression (3DR) independent of glycaemic control." (PMID 35182158, 2022). "Data from the Adolescent Type 1 Diabetes Cardiorenal Intervention Trial (AdDIT) trial demonstrated greater age- and sex-adjusted pulse wave velocity and greater aortic intima media thickness in adolescents with T1D with higher albumin excretion." (PMID 34638531, 2021). "Of the THAs with data available, there were 2292 (4.8%) THAs with BMI ≥40 kg/m2, 2242 (8.7%) THAs with albumin <3.5 g/dL, 3177 (6.6%) THAs who were current tobacco users, 1628 (3.4%) THAs with insulin-dependent diabetes, and 5187 (10.8%) THAs with non–insulin-dependent diabetes." (PMID 34277906, 2021). "Patients with type 1 diabetes develop tissue abnormalities and break down in homeostasis in blood flow and glomeruli vascular permeability that are indicated by abnormal levels of albumin in the urine, a condition referred as microalbuminuria." (PMID 34233296, 2021). "We examined whether candidate biomarkers in serum or urine can improve the prediction of renal disease progression in type 1 diabetes beyond prior eGFR, comparing their performance with urinary albumin/creatinine ratio (ACR)." (PMID 31915892, 2020). "In addition to ameliorating renal inflammation as shown by mitigated NF-κB activities and IL-6 levels, EMP reduced glomerular hyperfiltration and urinary albumin excretions in the Akita mice model of type 1 diabetes." (PMID 31168342, 2019). "There is now evidence to indicate that replacement of C-peptide in type 1 diabetes is accompanied by improved renal function, as evidenced by correction of glomerular hyperfiltration and diminished urinary albumin excretion, and amelioration of nerve dysfunction." (PMID 20535267, 2010). "We previously examined whether increased urinary AGT excretion is present prior to the onset of urinary albumin in streptozotocin-induced type 1 diabetic mice; we found that urinary AGT may be useful as an early biomarker of the activation of the RAS in experimental type 1 diabetes." (PMID 40003909, 2025). "In a cohort study of patients with type 1 diabetes mellitus and proteinuria, baseline serum KIM-1 levels were a strong predictor of eGFR loss and ESKD during the 5 to 15 years of follow-up after adjusting their values for baseline urinary albumin-to-creatinine ratio levels, eGFR, and Hb1Ac." (PMID 37189380, 2023).
type 1 diabetes (continued). "G/C polymorphism at the position-174 in IL-6 promotor region (rs1800795) has been found to correlate with retinopathy, nephropathy, increased albumin-to-creatinine ratio as well as poor glycemic control and hyperlipidemia in Type 1 diabetes mellitus (T1DM)." (PMID 33016995, 2020). "In another study, urinary albumin excretion along with heart rate variability significantly improved in type 1 diabetic patients who received 6-month combination treatment of C-peptide and insulin, indicating that C-peptide and insulin improve renal and autonomic nerve function in type 1 diabetes." (PMID 30430334, 2019). "In type 1 diabetes, kidney damage is more common in men whose SUA and creatinine concentrations and the albumin excretion rate are higher than those in female patients." (PMID 31737070, 2019). "In type 1 diabetes model mice induced by STZ treatment, urinary albumin excretion was detectable at 8 weeks after treatment, then significantly increased compared to the control group at 12 weeks or later, indicating the possible presence of kidney damage in the model mice." (PMID 27033449, 2016). "Without specific intervention, 80% of type I diabetic patients that develop microalbuminuria will evolve to macroalbuminuria (albumin excretion >300 mg/g creatinine) at an average time of 10–15 years." (PMID 26239461, 2015). "A recent clinical study has reported that empagliflozin ameliorated hyperfiltration, but not the urine albumin/creatinine ratio in patients with type 1 diabetes." (PMID 24960177, 2014). "However, a limitation was that antibodies to many individual milk proteins (bovine serum albumin, β-lactoglobuline, or bovine insulin), which have been related to type 1 diabetes in previous studies, were not available." (PMID 38906178, 2024). "However, children with type-1 diabetes and celiac disease excrete lower levels of albumin than type-1 diabetic children without celiac disease, suggesting a protective role for celiac disease." (PMID 24678255, 2013). "Also, C-peptide enhances skeletal muscle and skin blood flow, augments nerve function, diminishes urinary albumin excretion, and decreases glomerular hyperfiltration, only in individuals who suffer from type 1 diabetes and lack of C-peptide, and not in those with healthy status." (PMID 37568168, 2023). "One study in patients with type 1 diabetes and nephropathy provided convincing evidence in this respect: in patients with adequate control of blood pressure, cessation of smoking significantly decreased urinary albumin excretion, although glycemia was not perfectly controlled." (PMID 19570254, 2002). "In a study on type 1 diabetic patients, the combination of L-FABP and albumin excretion rate did not improve the ROC-AUC compared with a single use of each parameter." (PMID 33033456, 2020).
non-small cell lung carcinoma (102 papers, 1996 to 2026). A group of at least three distinct histological types of lung cancer, including non-small cell squamous cell carcinoma, adenocarcinoma, and large cell carcinoma. "A total of 387 NCSLC patients of all stages were included in the “post-diagnostic C-reactive protein and albumin predict survival in Chinese patients with non-small-cell lung cancer: a prospective cohort study”." (PMID 38540301, 2024). "The ALB–alkaline phosphatase ratio can be used as a novel risk stratification tool to improve prognostic prediction in patients with non-small cell lung cancer who are undergoing surgery." (PMID 36428725, 2022). "The extent of weight loss, albumin, C-reactive protein, performance status and quality of life was measured in 106 patients with inoperable non-small cell lung cancer (stages III and IV)." (PMID 12177792, 2002). "Furthermore, a reduced level of serum albumin was determined as a standalone factor that was significantly linked to a worse outcome in patients with Stage IIIB non-small cell lung cancer." (PMID 39512692, 2024). "Additionally, the high expression of caveolin-1 in tumor stroma, a significant component of caveolae, has been associated with improved responses to albumin-conjugated drugs in non-small cell lung cancer (NSCLC) patients." (PMID 38203730, 2023). "Patients treated with PTX or nanoparticle albumin-bound paclitaxel (nab-PTX) combined with platinum-based anticancer regimens for non-small cell lung cancer between January 2019 and September 2024 were included in this study." (PMID 42199866, 2026). "Our findings show that among the investigated inflammatory indices, C-reactive protein/albumin ratio has the highest prognostic value in patients with metastatic non-small cell lung cancer." (PMID 40465984, 2025). "As another exciting example, Abraxane® (albumin-bound paclitaxel nanoparticles) is approved for the treatment of metastatic breast cancer, non-small cell lung cancer (NSCLC), and pancreatic cancer." (PMID 39897552, 2025). "Albumin-bound paclitaxel is frequently used in various cancer treatments, including in non-small cell lung cancer (NSCLC), due to its strong targeting capability and low toxicity." (PMID 39296984, 2024). "From the results of bibliometric analysis, literature related to albumin and non-small cell lung cancer show an increasing trend." (PMID 37036321, 2023). "In non-small cell lung cancer (NSCLC), CPR, ALB, PNI and NLR were reported to be associated with the response to ICIs." (PMID 34992504, 2021). "The GPS staging system was firstly established in inoperable non-small-cell lung cancer, with two major evaluative dimensions: serum ALB and CRP." (PMID 34221991, 2021). "The GPS was first presented as a scoring system based on a combination of CRP and albumin in patients with inoperable non-small cell lung cancer." (PMID 33227100, 2020). "This comprises albumin-conjugated paclitaxel, being used in metastatic breast cancer and non-small-cell lung cancer." (PMID 31973051, 2020). "The purpose of this study was to evaluate the efficacy and safety of nanoparticle albumin-bound paclitaxel as a rescue regimen in the treatment of patients with advanced non-small-cell lung cancer." (PMID 23554745, 2012). "In summary, weekly-administered albumin-bound paclitaxel seems to be an effective and safe regimen for elderly patients with stage IV non-small-cell lung cancer who were refractory to conventional therapy." (PMID 23554745, 2012). "The GPS was originally developed, from the combination of C-reactive protein and albumin, in a cohort of patients with advanced non-small cell lung cancer." (PMID 21266974, 2011). "It is of interest that recent machine learning models of prognostic factors, in patients with non-small cell lung cancer receiving immunotherapy in the context of a randomized trial, have identified albumin, CRP, LDH and neutrophils as independent prognostic factors." (PMID 40133911, 2025).
non-small cell lung carcinoma (continued). "Albumin nanocapsules were designed to improve treatments for non-small cell lung cancer (NSCLC)." (PMID 39771506, 2024). "Albumin-to-alkaline phosphatase ratio (AAPR) is the ratio of serum albumin to alkaline phosphatase, and its predictive value for patients' prognosis has been confirmed in many malignant tumors, including non-small cell lung cancer, renal cancer, and nasopharyngeal carcinoma." (PMID 39010005, 2024). "After FDR correction, associations remained significant between small cell lung cancer and creatinine, eGFR, cystatin C, glycated haemoglobin A1c, non-small cell lung cancer and albumin, lung squamous cell carcinoma and eGFR, creatinine, cystatin C. Lung adenocarcinoma and alkaline phosphatase." (PMID 39687887, 2024). "For non-small cell lung cancer, a negative causal relationship was found with albumin (β=-0.024, P=0.002, FDR=0.016*), while a potentially positive causal relationship was observed with cystatin C (β=0.022, P=0.006, FDR=0.054)." (PMID 39687887, 2024). "The acute inflammatory, as manifest by alterations in white cell count and circulating concentrations of acute-phase proteins, C-reactive protein (CRP), and albumin, has been shown to be an independent prognostic factor in various cancers including non-small cell lung cancer (NSCLC)." (PMID 21569644, 2011). "Indeed, this relationship between nutritional decline, albumin concentrations and the systemic inflammatory response has recently been exploited to form a new prognostic score in patients with advanced non-small-cell lung cancer." (PMID 15213726, 2004). "Markers of the inflammatory response, interleukin 6, C-reactive protein, albumin and full blood count, were measured in non-small-cell lung cancer (NSCLC) patients (n = 21) with and without weight loss ( > 5%)." (PMID 8664130, 1996). "Furthermore, different studies have shown albumin-based nanoparticles involved in anticancer therapies in clinical trials; one example is the nanocomposite Abraxane, adopted as therapeutic agent for pancreatic cancer, non-small cell lung cancer, and breast cancer." (PMID 39339208, 2024). "The ALI is a combination of the ALB, BMI and NLR and has been proven to be related to the prognosis of non-small cell lung cancer, gastrointestinal tumours, diffuse large B-cell lymphoma, head and neck tumours, etc." (PMID 38918730, 2024). "In addition to advanced non-small cell lung cancer, nanoparticle albumin-bound paclitaxel (nab-PTX) may also harbor potential benefit for patients with relapsed small cell lung cancer (SCLC), since weekly paclitaxel (PTX) shows modest activity for relapsed SCLC." (PMID 35147134, 2022). "The GPS was the index reported in non-small lung cell cancer by Macmillan, and the GPS combines CRP and ALB and evaluates blood protein moieties primarily." (PMID 35356942, 2022). "Abraxane® is an FDA-approved albumin-nanoparticle formulation of PTX which utilizes this mechanism as first line treatment for metastatic breast cancer, advanced non-small cell lung cancer (NSCLC) and late-stage (metastatic) pancreatic cancer." (PMID 34727233, 2021). "Meanwhile, the albumin-globulin score (AGS) has been proposed as another prognostic model to predict the prognosis of certain tumors, such as non-small cell lung cancer and esophageal squamous carcinoma." (PMID 34631767, 2021). "The albumin-based protein-bound paclitaxel Abraxane has been approved by the FDA for the treatment of breast cancer, non-small cell lung cancer (NSCLC) and pancreatic cancer showing stability, efficacy, and reduced toxicity towards the soluble drug." (PMID 32668783, 2020). "Non-squamous, non-small-cell lung cancer patients: pemetrexed (500 mg/m2, d1) plus carboplatin (AUC = 5; d1, Q3W); lung squamous cell carcinoma patients: albumin-bound paclitaxel (100 mg/m2, d1, d8 and d15) plus cisplatin (75 mg/m2, d1, Q3W)." (PMID 41583476, 2025).